ALMS1P1 (ALMS1 pseudogene 1)
Synonyms: formerly ALMS1L; ALMS1P
Gene: Transcribed unprocessed pseudogene on chromosome 2 (73,671,030 to 73,685,085, forward strand). Ensembl gene ENSG00000163016.
Diseases named in the same sentence as ALMS1P1 in open-access papers:
ALMS1P1 is named in the same sentence as 1 disease in open-access papers, as found by Europe PMC text mining. Sharing a sentence is not in itself a finding about the gene and the disease.
ALMS1P1 shares sentences with these, for which no sentence is quoted: pancreatic carcinoma (1 paper).